RNU6-785P (RNA, U6 small nuclear 785, pseudogene)
Gene: Small nuclear RNA gene on chromosome 9 (138,259,595 to 138,259,698, forward strand). Ensembl gene ENSG00000223256.
Homologues: Orthologues: chimpanzee U6 (100% identical), macaque U6 (91% identical), pig U6 (84% identical), pig U6 (78% identical), dog U6 (77% identical). Paralogues in human: RNU6-1076P (100% identical), RNU6-1100P (100% identical), RNU6-1118P (100% identical), RNU6-1217P (100% identical), RNU6-355P (100% identical), RNU6-447P (100% identical), RNU6-791P (100% identical), RNU6-860P (100% identical), U6 (100% identical), RNU6-1054P (99% identical), RNU6-1199P (99% identical), RNU6-1319P (99% identical), and 1289 more.